VHL (von Hippel-Lindau tumor suppressor)
Diseases named in the same sentence as VHL in open-access papers (continued):
Sharing a sentence is not in itself a finding about the gene and the disease.
tumor (continued). "Together with our previous finding that MT1-MMP expression is regulated by HIF-2α in VHL null cells, our data suggest that one mechanism by which VHL may inhibit tumor invasion is by suppressing MT1-MMP expression through the negative regulation of HIF-2α protein." (PMID 17140440, 2006). "Although a 'second hit' which usually consists of deletion in the wild-type VHL allele, is necessary for initiation of tumor growth in patients with VHL germline mutations, it may not be sufficient." (PMID 16707008, 2006). "This review highlights how compounds such as curcumin, resveratrol, quercetin, and epigallocatechin-3-gallate modulate the VHL-HIF axis, disrupt metabolic and redox homeostasis, and influence tumor-immune system interactions in ccRCC." (PMID 42196561, 2026). "Either ALKBH5 knockout or MANF ablation had a more noticeable effect on VHL inactivation 786-O, suggested tumor cell ER stress protective effects and mechanisms of MANF was affected by VHL status." (PMID 40603319, 2025). "Its knockdown drives HDAC2 translocation to the nucleoplasm, increasing occupancy on VHL and VDAC1 promoters, thereby enhancing glycolysis and glutaminolysis to support tumor survival and growth." (PMID 41361062, 2025). "According to the latest research, variations in the VHL, PBRM1, and SETD2 genes are the strongest evidence for tumor growth and how it responds to therapy." (PMID 41479787, 2025). "This combination treatment leads to G1/S phase arrest in drug-resistant cells, increased tumor growth inhibition (TGI) rate, and complete remission (CR) rate by targeting the PI3K-AKT-mTOR and VHL-HIF pathways to overcome sorafenib resistance." (PMID 41282606, 2025). "Functional validation revealed tumor-suppressive roles of L3MBTL2 and VHL, highlighting their potential as therapeutic targets in STAD." (PMID 40821814, 2025). "By regulating key processes such as cell cycle, DNA repair, signal transduction, and hypoxia response, these enzymes can both promote tumor development as oncogenes (e.g. MDM2) and inhibit cancer as tumor suppressor genes (e.g. BRCA1, VHL)." (PMID 40276056, 2025). "To enrich for oxygen responsiveness in VHL-corrected RCC2 cells and preserve the tumor cell heterogeneity, we developed a three-step strategy." (PMID 41301058, 2025). "VHL knockdown in ccRCC leads to HIF-1α/2α accumulation, which upregulates N-cadherin and vimentin while suppressing E-cadherin, ultimately facilitating tumor invasion." (PMID 41208892, 2025). "Aberrant methylation of genes such as VHL, RASSF1A, and CDH1 can be detected in plasma, enabling early tumor detection and differentiation between malignant and benign renal lesions." (PMID 41479787, 2025). "The role of CCT complex in this context, particularly in relation to the impaired function of PHD3, VHL and HIF-1α, warrants further investigation to elucidate its potential impact on HIF-dependent signaling and tumor biology." (PMID 41516249, 2025). "The VHL gene primarily affects tumor development by regulating the hypoxia response, whereas the PBRM1 gene contributes to tumor development through chromatin remodeling and immune regulation." (PMID 40969770, 2025). "Similar to the 786-0 tumor lines, we observed an increased rate of OXPHOS, and the metabolic gene expression shifts due to the re-expressed WT VHL." (PMID 41301058, 2025). "This selectivity is likely due to the differential expression of VHL between tumor cells and normal tissues, allowing FP54 to target and degrade FTO more specifically in tumor cells while sparing normal cells." (PMID 40815637, 2025). "Consequently, while VHL mutations are commonly observed in ccRCC, they do not necessarily dictate tumor progression or prognosis and may be associated with other intricate molecular mechanisms." (PMID 40028163, 2025). "COM exposure led to the downregulation of well-established RCC tumor suppressor genes, including ARID1A, PTEN, and VHL, while significantly increasing TPX2 expression." (PMID 40362354, 2025).
tumor (continued). "Such molecules only target classical proteins such as VHL and MDM2,173 which means that there are still limitations in tumor treatment." (PMID 39759114, 2025). "Under hypoxia, ID2 directly binds and disrupts the VHL-Elongin C complex, stabilizing the HIF in tumor cells and promoting survival during metabolic stress (left side)." (PMID 41155273, 2025). "This review focuses on understanding the VHL/HIF signaling axis in GBM, its implications in tumor development, and its potential as a therapeutic target for the treatment of brain tumors." (PMID 41155273, 2025). "Inhibition of HIF-PH activity by iron chelators are expected to boost tumor immune response by upregulating HIF in CD8+ T cells, akin to VHL knockdown." (PMID 40343532, 2025). "For example, VHL inactivation and subsequent HIF-dependent signaling pathways enhance apoptotic resistance in tumor cells." (PMID 41584840, 2025). "The inactivation of the VHL gene leads to the stabilisation of HIF-2α, activates the expression of downstream genes, and promotes the proliferation and survival of tumor cells." (PMID 41555916, 2025). "Specifically, Mei‐based molecular glues and Mei‐derived PROTACs, such as CRBN‐type and VHL‐type PROTACs, can be designed and synthesized to enhance the degradation of PKMYT1, thereby exhibiting more potent tumor suppressive effects." (PMID 40279509, 2025). "However, VHL mutation is not sufficient to promote tumor formation." (PMID 39050705, 2024). "In IGHV-unmutated cases, they reported methylation of known or potent tumor suppressor genes (for example, VHL, ABI3, and IGSF4) as well as unmethylated genes involved in cell growth and tumor progression (ADORA3 and PRF1)." (PMID 38435839, 2024). "In our animal experiments, we established that ANGPTL4 significantly suppresses tumor growth in human CAKi-1 and mouse Renca RCC cells with WT VHL." (PMID 39105498, 2024). "Knockout of ANGPTL4 in 786O cells which have mutant VHL, significantly reduced tumor growth as did treatment with anti-cANGPTL4 antibodies, suggesting that in 786O cells, the proangiogenic tumor-promoting function of cANGPTL4 may be predominant over the tumor suppressive function." (PMID 39105498, 2024). "To understand the effect of ANGPTL4 on tumor progression, we used CRISPR-Cas9 to generate KO of ANGPTL4 in CAKi-1 cells, a human ccRCC cell line that has WT VHL." (PMID 39105498, 2024). "In terms of the mechanism, we found that miR-21-5p carried by TAM-EVs activated HIF-1α in ECs through VHL and LATS1, forming a YAP1/HIF-1 positive loop, which plays a crucial role in promoting tumor angiogenesis." (PMID 38602536, 2024). "We showed that depletion of PHD1 or reconstituted expression of Beclin1 P54A disrupted the binding of VHL to Beclin1 with correspondingly increased interaction between ATG14L and Beclin1 in these tumor cells." (PMID 38360997, 2024). "However, whether VHL possesses HIF-independent tumor-suppressing activity remains largely unclear." (PMID 38360997, 2024). "Consistent with this, T cells in which VHL or all three PHDs (PHD1-3) are knocked out have increased HIF levels, boosted effector responses and confer improved anti-tumour control." (PMID 38690263, 2024). "The identified epigenetic PARPi hallmarks contained hundreds of DMRs; however, only a few DMRs were reported as tumor driver genes (SOX2, POU2AF1, PTK6, VHL, JAK3, and EZH2) or as HRD genes (RAD51C)." (PMID 38927686, 2024). "Deletion of CBF-β with two independent sgRNAs both substantially impeded tumour growth and prevented metastasis to the lungs, confirming the relevance of the CBF-β/VHL synthetic lethality in vivo." (PMID 39282259, 2024). "Moreover, in this study, VHL represented the predominant group of mutations (50.5%) but significant results were founded only for BAP1 mutation and its association with ill-defined tumor margins and the presence of calcification and for MUC4 mutation and its connection with exophitic growth." (PMID 38666933, 2024).
tumor (continued). "The synthetic lethal interaction between VHL and CBFB provides a new route to target ccRCCs, and is supported by our murine xenograft models in which tumour growth is markedly inhibited." (PMID 39282259, 2024). "CREB5 has an effect similar to that of VHL; under hypoxic conditions, CREB5 promotes tumor angiogenesis." (PMID 38191389, 2024). "Specifically, the LIMD1 gene responds to hypoxia through an HIF1-α response element in its promoter and, as a protein, acts as a scaffold to stabilize the PHD2/VHL/HIF-1α degradation complex, in this sense working as a tumor suppressor." (PMID 38794149, 2024). "When SPNpros were delivered to tumor tissues, the peptides were specifically cleaved by tumor-overexpressed cathepsin B to release free IDO-degrading PROTACs and the free PROTACs mediated IDO degradation utilizing the VHL E3 ligase-UPS pathway." (PMID 36839734, 2023). "Namely, alterations in VHL lead to overexpression of Vascular Endothelial Growth Factor (VEGF) and several other growth factors, resulting in endothelial cell migration, tumor angiogenesis, and tumor growth." (PMID 35674770, 2023). "Reconstitution of von Hippel–Lindau protein (VHL) in RCC cell lines with lost VHL brings back the LC3C, and subsequent LC3C knockdowns lead to tumor formation despite the presence of VHL." (PMID 37003503, 2023). "Given the critical roles that VHL and VEGF pathways play in RCC tumorigenesis and anti-tumor immunity, studies have been surprisingly ambiguous in terms of the utility of these biomarkers for predicting response to ICIs." (PMID 37568390, 2023). "We identified 146 (13.6%) tumor-essential E3 ligases (mean of probabilities of essentiality across cell lines >0.563) in CRISPR screening, including two co-opted E3 ligases, VHL and RNF4." (PMID 37845222, 2023). "To study the impact of intratumoral VHL heterogeneity observed in human ccRCC, we engineered VHL gene deletion in four RCC models, including a new primary tumor cell line derived from an aggressive metastatic case." (PMID 37069149, 2023). "In our second study on VHL in PTC, we compared the expression levels of VHL mRNA in another tumor series consisting of 42 pairs of PTCs and matched non-tumor thyroid tissues." (PMID 36036061, 2023). "IHC of VHL and POSTN in serial sections of the primary tumor of case #22 showed that VHL+ areas were POSTN negative (POSTN−) whereas VHL− areas stained positive for POSTN (POSTN+)." (PMID 37069149, 2023). "They found that DRD2 interacted with von Hippel-Lindau (VHL) in the nucleus, and competitive binding of DRD2 and HIF-1α to VHL resulted in reduced ubiquitination-mediated degradation of HIF-1α, enhancing the epithelial-mesenchymal transition of tumor cells." (PMID 37415171, 2023). "The “Use with Caution” antibodies in this set include antibodies that bind the protein products of frequently altered cancer driver genes, such as the oncogenes MYC and BRAF and the tumour suppressors BRCA2 and VHL." (PMID 37169592, 2023). "For instance, disruption of VHL and EZH1, SLC2A1, ROCK1, SKP2, AURKA, or TBK1 genes can each inhibit cancer progression by inducing the death of tumor cells." (PMID 37190141, 2023). "We further provide preclinical evidence demonstrating that targeting CDK1/PIN1 axis is a common and effective approach to suppress tumor progression of TNBC and other cancers harboring wild-type VHL including TNBC." (PMID 36813923, 2023). "Only in one primary tumor, we detected cn-LOH at the chromosomal region 3p21.31-p21.1, which harbors the tumor suppressor gene von Hippel-Lindau (VHL)." (PMID 38010391, 2023). "Studies have found that UBE2S can specifically ubiquitinate and degrade VHL via the 26S proteasome to stabilize hypoxia‐inducible factor (HIF) and eventually promote tumor progression." (PMID 37563971, 2023). "Knockout of DEPTOR, moreover contributed to enhanced tumor cell proliferation in VHL competent cells, whereas, restoration of DEPTOR expression in ccRCC cells inhibited tumor growth." (PMID 36831657, 2023).
tumor (continued). "Overexpression of CatB in tumor cells facilitated the releaseof the activated CPP, which then bound to Von Hippel Lindau (VHL)E3 ubiquitin ligase and COX-1/2 through a VHL-targeting segment (GSGSALAPYIP)and indomethacin (IND), respectively." (PMID 37901179, 2023). "To further elicit better predictors amongst the range of PD-L1 expression in tumor tissues, we grouped the samples based on three genetic backgrounds: sporadic cases, pseudohypoxia cluster (SDHB, VHL, EGLN1, EPAS1) and kinase signaling cluster (RET, NF1)." (PMID 36439433, 2022). "However, in VHL-deficient cells with high FTO expression, PGC-1α expression is induced via a decrease in m6A methylation, which restores mitochondrial activity and promotes oxidative stress (OS) and ROS production, with consequent inhibition of tumor progression." (PMID 35794625, 2022). "The interaction between VHL and HIF1A indicating the involvement of the same pathway to suppress tumor activity." (PMID 35399005, 2022). "For cases with available panel sequencing of primary tumor tissue, the concordance with sequence variations in PDX tumors identified by RNAseq ranged between 75% (ARID1A) and 100% (VHL)." (PMID 35800063, 2022). "Compared with normal renal cells, cells from the two tumor samples had high levels of the HIF metagene (p < 2 × 10−16, Wilcoxon rank-sum test), consistent with inactivation of VHL and constitutive stabilization of HIF in tumor cells." (PMID 36384128, 2022). "It is well known that Hippel-Lindau(VHL) play a critical tumor suppressor role in KIRC, and VHL gene inactivation is by far the most common carcinogenic driving event in KIRC." (PMID 35475392, 2022). "The lncRNA SNHG11 binds to the VHL recognition site on HIF-1α, thereby blocking the interaction of VHL and HIF-1α, preventing its ubiquitination and degradation, and promoting tumor metastasis." (PMID 35392171, 2022). "Tumor analysis revealed characteristic cytomorphological, immunohistochemical reactivity for alpha-inhibin, and CAIX, and reduced pVHL reactivity supported VHL-related pseudohypoxia." (PMID 35304467, 2022). "Hypoxia conditions and VHL inactivation lead to the expression of VEGF, promoting angiogenesis and tumor growth." (PMID 35892875, 2022). "However, VHL loss alone is not sufficient to induce tumor formation." (PMID 36059687, 2022). "VHL tumor suppressor protein can play a role in tumor suppression in multiple ways and the most common of them is targeting the HIF that mediated tumor suppression activity through polyubiquitylation and proteasomal degradation." (PMID 35399005, 2022). "Indeed, a very frequent mutation of the tumour suppressor gene VHL in ccRCC (>80% of cases) dysregulates hypoxia-inducing factor (HIF) inducing overexpression of vascular endothelial growth factor A (VEGF-A) and platelet-derived growth factor (PDGF) leading to tumour growth." (PMID 36551652, 2022). "The inactivation of the Von Hippel–Lindau Tumor Suppressor (VHL) gene and the activation of Hypoxia-Inducible Factor (HIF) promote the production of VEGF, while sunitinib blocks this process and plays an anti-tumor role." (PMID 35205613, 2022). "We should note that our result showed a low level of persistent tumor signals in the kidney despite VHL restoration, suggesting that VHL gene therapy, even if it is developed, may still require a combination with other therapeutic modalities for complete tumor eradication." (PMID 35159281, 2022). "However, no significant gene mutations, including VHL gene were detected in our tumor." (PMID 35220972, 2022).